MYCN (MYCN proto-oncogene, bHLH transcription factor)
Diseases named in the same sentence as MYCN in open-access papers (continued):
Sharing a sentence is not in itself a finding about the gene and the disease.
tumor (continued). "Immunoinfiltration analysis revealed differences in composition and levels of immune cells within the tumor microenvironment between MYCN‐amplified and non‐amplified cases." (PMID 40600620, 2025). "DNA methylation profiling of the tumor was performed, which suggested the diagnosis of diffuse pediatric-type high grade glioma, MYCN subtype." (PMID 41155159, 2025). "Age, COG score, MYCN gene expression, tumor tissue differentiation, and NR2F6 expression were included to construct multifactorial linear regression equations." (PMID 40424451, 2025). "ALKF1174L cooperated with MYCN to shorten the latency of tumor formation compared to MYCN alone (51–65 vs. 65–125 days, respectively)." (PMID 38451815, 2024). "Patient‐derived tumor organoids and cell line models demonstrated ceftriaxone's selectivity in targeting MYCN‐driven cancer cells through DDX3X inhibition, suppressing translation." (PMID 37975412, 2024). "Using patient‐derived tumor organoids and tumor cell lines, we demonstrated that ceftriaxone is a potent and selective growth inhibitor targeting MYCN‐driven RB and NB cells." (PMID 37975412, 2024). "In various NB initiation and progression models, elevated levels of LIN28B, MYCN and ODC1 have been associated with increased tumor initiation and progression due to increased proto‐oncogene activity and ensuing progenitor‐like cells." (PMID 38686627, 2024). "Conversely, treatment of MYCN tumor cells with the GSK3β inhibitor CHIR99021 (WNT activator) increased periostin." (PMID 38451815, 2024). "The suppressed tumor phenotype was retained on both backgrounds when compared to normal Th-MYCN mice backcrossed using the same strategy." (PMID 38992040, 2024). "Genetic knockdown of MTHFD1 or application of folic acid inhibitor MTX combined with JQ1 can synergistically inhibit tumor progression in MYCN-amplified NB." (PMID 38336749, 2024). "Drug potency also indicated that the response of MYCN‐driven RB to ceftriaxone was distinguishable from other RB tumor cells but similar to NB with MYCN amplification." (PMID 37975412, 2024). "Collectively, these results indicate that SESN1 is a downstream target of MYCN and functions as a tumor suppressor gene in NB." (PMID 38516781, 2024). "The most common cytogenetic changes include deletions of chromosome 1p, amplification of the oncogene MYCN, ploidy changes, gains of chromosome arm 17q and deletion of 11q in tumor cells." (PMID 39049899, 2024). "Compared with other spinal ependymomas, MYCN-amplified spinal ependymoma is an aggressive tumor with low progression-free and overall survival rates." (PMID 38544524, 2024). "The Th-MYCN+/−; Runx1t1+/+ mice displayed 9.9% tumor incidence (18/181), as compared to 0.87% (3/343) in Th-MYCN+/−; Runx1t1+/− mice." (PMID 38992040, 2024). "In contrast, TrkB is expressed more often in tumours with a worse prognosis and with amplification of MYCN." (PMID 38542729, 2024). "This suggests that MYCN overexpression can bypass the necessity to deactivate p107 or p130 for tumor development." (PMID 39000021, 2024). "AURKA inhibitors have been demonstrated to be effective against MYCN‐amplified NB tumour models, via degradation of abundant N‐Myc oncoproteins, leading to apoptotic cell death." (PMID 39501501, 2024). "Among the numerous, prognostic variables are disease stage, age at diagnosis, tumor pathology, tumor cell ploidy, and MYCN amplification status, which can help distinguish the disease’s characteristics and predict the clinical outcome." (PMID 38339295, 2024). "We thus became interested in CAMKV, which was previously correlated to a worse NB patient survival and whose mRNA expression is highly associated to that of MYCN or MYC in NB cell lines and primary tumor samples." (PMID 38255303, 2024). "As observed with RK‐33, MYCN‐amplified tumors were most susceptible to translation repression by ceftriaxone, followed by c‐MYC‐expressing tumor cells treated with high drug doses." (PMID 37975412, 2024).
tumor (continued). "The observed transcriptional heterogeneity was surprising, given that most tumour cells appeared karyotypically homogeneous (including a chr17q gain) and expressed MYCN." (PMID 38702304, 2024). "In contrast, mice treated with oral opaganib had substantially reduced rates of tumor growth, indicating antitumor activity against human NB cells with amplified MYCN." (PMID 38730731, 2024). "Amplification of MYCN and deletion at 11q are established prognostic markers for NB with poor outcome, where MYCN amplification is present in 20–30% and 11q deletion is present in 35–45% of all NB tumours." (PMID 39217334, 2024). "The MYCN gene plays a critical role in impairing apoptosis and stimulating tumor growth, contributing to reduction of therapeutic effects." (PMID 38826727, 2024). "HSF1 regulates MYCN transcription by binding to both its promoter and SE regions, thereby promoting tumor cell growth." (PMID 39248163, 2024). "DOX treatment of 17q1qMYCN resulted in robust induction of MYCN, similar to expression levels in MYCN-amplified tumours." (PMID 38702304, 2024). "Next, we compared the activity levels of WNT and YAP signaling in ALK/MYCN tumor cells with control single guide RNA (sgRNA) or POSTN sgRNA." (PMID 38451815, 2024). "In one study, tyrosine-hydroxylase-MYCN (TH-MYCN) homozygous mice were monitored for tumor-induced inflammation and growth in vivo." (PMID 39445288, 2024). "Aggressive tumours with MYCN amplification tend to be more resistant to oxidative stress due to the increased transcription of glutathione." (PMID 38542729, 2024). "For comparison, injection of cells from a MYCN-amplified NB cell line (SK-N-BE2C-H2B-GFP69) resulted in engraftment with subsequent tumour cell growth in 84% of larvae." (PMID 38702304, 2024). "Tumor aggressiveness driven by MYCN can be acquired via dysregulation of MYCN-dependent genes, including long non-coding (lnc)RNAs, a type of non-coding RNAs." (PMID 38689348, 2024). "MYCN amplification is a known marker of tumor progression and resistance in NB, and EVs derived from MYCN-amplified NB (SK-N-BE2) cells were found to impart doxorubicin-resistance to non-MYCN amplified recipient SH-SY5Y cells." (PMID 38660306, 2024). "Specifically, we set up 1200 heterogeneous tumours and tracked the MYCN-amplified clone’s dynamics in each, revealed the conditions that favour its growth, and tested its responses to 5000 drug combinations." (PMID 39715281, 2024). "In MYCN-amplified NBs, MYCN was found to transfer such aggressive, oncogenic phenotype to other non-MYCN amplified NB cells and surrounding stromal cells by regulating the host cell EV-protein cargo thereby promoting tumor progression." (PMID 38660306, 2024). "The most significant of the genetic biomarkers of NB known so far remains the amplification of the MYCN gene, which regulates the metabolic pathways of the tumor, and its levels correlate with the course of the disease." (PMID 39062971, 2024). "To further investigate how WNT and periostin influenced each other, we first treated ALK/MYCN tumor cells with the WNT inhibitor WNT-C59 at 10 μM for 48 h." (PMID 38451815, 2024). "Taken together, these data indicate that KAP1 interacts with YTHDC1 to regulate the stability of MYCN mRNA and sustain NB tumor malignancy." (PMID 38745192, 2024). "Tumors derived from MYCN-PRDM6 NES cells clustered with SHH medulloblastomas as well, suggesting that MYCN has a dominant effect on tumor phenotype." (PMID 38992221, 2024). "Taken together, these findings implicate Runx1t1 as a potential modifier responsible for the increased tumor penetrance in 129/SvJ Th-MYCN mice." (PMID 38992040, 2024). "Five (33.3%) of the patients with MYCN amplification had a tumor mass in the abdomen and ten (66.7%) had a tumor mass in the adrenal gland." (PMID 39049899, 2024). "MYCN withdrawal, on the other hand, abated cancer stemness properties of tumor-propagating cells in a MYCN-dependent MB mouse model." (PMID 38689348, 2024).
tumor (continued). "To evaluate the impact of combined PRDM6 and MYCN overexpression on tumor formation, we performed orthotopic transplantation experiments in mice." (PMID 38992221, 2024). "None of the DMC cells display any overt ganglion cell markers as several of the type 2 cancers do, or that is seen in tumours after MYCN expression in foetal human retina transduced in vitro and xenografted to mice." (PMID 37606819, 2024). "To stimulate immune activation in Th-MYCN model, we primed the tumor microenvironment by administering the copper chelating agent TEPA daily for 1 week, followed by the addition of twice weekly doses of anti-GD2 antibody." (PMID 39668192, 2024). "The independent factors that predict the outcome of treatment are: tumor histology, level of MYCN amplification and chromosomal copy number changes." (PMID 39049899, 2024). "The MYCN‐status‐dependent sensitivity of tumor cells to RK‐33 suggests selective effects of DDX3X inhibition on MYCN‐amplified tumors." (PMID 37975412, 2024). "In patients with localized NB harboring MYCN amplification, extended surgery of the primary tumor site improved the local control rate and survival." (PMID 38070095, 2024). "Extending the in-vitro reference mapping to all ten tumours portrayed a spectrum of MYCN-amplified cells with a majority C13- or C14-like expression profile, and a subset of cells mapping to other differentiating trunk NC cell states." (PMID 38702304, 2024). "Intriguingly, cell‐cycle progression remained unaffected in MYCN‐nonamplified RB and NB cells when exposed to the highest dose of the drug (8 mm) applied to MYCN‐driven tumor cells." (PMID 37975412, 2024). "Correlation analyses underscored the influence of tumor entity and MYCN amplification on ganglioside expression and suggested an involvement of MYCN in the accumulation of GD2." (PMID 39449099, 2024). "In this work, an AMXT-1501/DFMO combination treatment delayed tumor development in a Th-MYCN-driven NB mouse model." (PMID 38858548, 2024). "In the current investigations employing the newer tricyclic sulfonamides, ATUX-3364 and ATUX-8385, tumor volumes, as well as relative tumor growth in animals bearing MYCN-amplified tumors, were significantly decreased." (PMID 39594793, 2024). "In our opinion, the gold standard for the assessment of MYCN amplification is fluorescence in situ hybridization on intraoperative tumor imprints." (PMID 39049899, 2024). "Two of the identified miRNAs (miR-29c and let-7b) are known regulators of MYCN, and miR-342-3p has previously shown to exert tumor suppressor functions in other cancer types." (PMID 38660306, 2024). "In contrast to the previous comparison, the differential reaction activity between NB -MYCN and NB +MYCN is overall smaller, since it is the same tumor entity." (PMID 39449099, 2024). "In this study, it was found that MTHFD1 played a tumor-promoting role in MYCN-amplified NB, and it promoted proliferation and migration but inhibited apoptosis of NB cells." (PMID 38336749, 2024). "Taken together, we successfully immortalized a RB tumor and stromal cell line, displaying a different MYCN status as well as individual expression of cancer-related proteins." (PMID 39695086, 2024). "Depletion of DDX3X inhibits protein synthesis, consistent with the observed translation repression after ceftriaxone and RK‐33 treatment of MYCN‐amplified tumor cells in our study." (PMID 37975412, 2024). "To this end, we collected scRNA-seq data from ten MYCN-amplified NB tumours from three independent sources." (PMID 38702304, 2024). "On the one hand, MYCN is capable of repressing antigens present in tumour cells to prevent recognition by the immune system." (PMID 38542729, 2024). "By contrast, type 2 tumours harbour frequently recurrent genetic alterations including MYCN-amplifications." (PMID 37606819, 2024).
tumor (continued). "For instance, the overexpression of the MYCN gene results in the inhibition of apoptotic signaling and induction of cell proliferation, and activating mutations in ALK promotes tumor growth, proliferation, and migration." (PMID 39338204, 2024). "As the BRD4 inhibitor, JQ1 can reduce the expression of MYCN and inhibit tumor growth in MYCN-amplified NB, but its effect seems unsatisfactory when used alone." (PMID 38336749, 2024). "Chromothripsis can cause SHH pathway gene amplification, such as GLI2 and MYCN, which increases SHH target gene expression and drives tumor development." (PMID 38391759, 2024). "Targeting the cofactors that mediate these 2 pathways antagonizes the dysregulated MYCN activity and more effectively suppresses NB tumor cell growth." (PMID 38547242, 2024). "Inhibiting MYCN mRNA m6A modification synergized with chemotherapy to restrain tumor progression in MYCN-amplified NB." (PMID 38745192, 2024). "The patients with heterogeneously MYCN-amplified tumours had higher lactate dehydrogenase (LDH) levels (predictor of poor clinical outcomes) than those with homogeneously MYCN-amplified tumours." (PMID 39715281, 2024). "Although the study suggests encouraging anti-tumor effects of gomisin B in MYCN-amplified NB cells, further exploration is required to understand its actual mechanism in regulating ESR1 and its interactions with chemotherapy drugs." (PMID 38313313, 2024). "Positive results for MYCN amplification have been observed in twelve patients’ paraffin-embedded tissue sections and in three patients’ intraoperative tumor imprints, which represents 22.4% of all patients tested in the analysis." (PMID 39049899, 2024). "To explore how ALKF1174L cooperates with MYCN to accelerate tumor growth, we performed RNA-seq on the MYCN and ALKF1174L/MYCN tumors (hereafter referred to as “ALK/MYCN”)." (PMID 38451815, 2024). "Positive results for MYCN amplification were observed in twelve patients’ paraffin-embedded tissue sections and in three patients’ intraoperative tumor imprints which represents 22.4% of all tested patients in the analysis." (PMID 39049899, 2024). "The gold standard in the assessment of MYCN amplification is fluorescence in situ hybridization on paraffin-embedded tissue sections and intraoperative tumor imprints." (PMID 39049899, 2024). "It was worth noting that, the P value between MTHFD1 expression and MYCN status was 0.058 in our observation, which ought to be verified with a larger sample size of tumor tissues." (PMID 38336749, 2024). "Previous studies demonstrate that DFMO treatment extends tumor latency and survival in NB‐prone mice that overexpress MYCN in neural crest cells." (PMID 38686627, 2024). "NB is characterized by significant genetic alterations, notably MYCN amplification and ALK mutations, which play pivotal roles in tumor initiation." (PMID 39458991, 2024). "Consistent with the literature, a MYCN-amplified clone’s expansion in a heterogeneous virtual tumour was contingent on the latter’s conditions, especially its genetic profile." (PMID 39715281, 2024). "To further characterize changes occurring during priming of the tumor microenvironment, we constructed a tissue microarray of Th-MYCN tumors consisting of untreated, control and TEPA-treated tumors resected after 3 and 7 days of treatment." (PMID 39668192, 2024). "MYCN amplification, ALK mutations, chromosomal abnormalities, changes in the pattern of DNA methylation, and tumor microenvironment are the primary molecular features in HRNBs." (PMID 38601081, 2024). "The IC50 values from each assay consistently indicated increased drug sensitivity in MYCN‐driven tumor cells and were dependent on the duration of antibiotic treatment." (PMID 37975412, 2024).
tumor (continued). "For each dataset, we curated MYCN+ tumour cells and bioinformatically mapped these to our reference." (PMID 38702304, 2024). "Collectively, our data put forward a CNA-driven distortion of trunk NC and sympathoadrenal differentiation as a priming mechanism for subsequent MYCN-induced tumour initiation." (PMID 38702304, 2024). "We then carried out simulations of MYCN-amplified clones’ dynamics in a broad range of heterogeneous tumours, revealing the conditions that promote their growth, and tested 5000 hypothetical combination therapies inhibiting 20 drug targets." (PMID 39715281, 2024). "Compared to mice injected with Daoy, those injected with Daoy-MYCN exhibited early-onset metastasis, a striking increase in the tumor burden, and a lower survival rate." (PMID 38689348, 2024). "Reciprocally, inhibition of the WNT pathway reduced expression of POSTN and growth of ALK/MYCN tumor cells." (PMID 38451815, 2024). "Altogether, ceftriaxone can post‐transcriptionally downregulate MYCN expression levels in MYCN‐amplified tumor cells." (PMID 37975412, 2024). "Our insights broaden the scope of this relationship to include the MYCN-amplified clone’s gene expression profile and the tumour’s microenvironment." (PMID 39715281, 2024). "Profiling of drug‐induced transcriptomic changes, cell‐cycle progression, and apoptotic death indicated cell‐cycle arrest and death of drug‐treated MYCN‐amplified tumor cells." (PMID 37975412, 2024). "Amplification of MYCN strongly predicts a poorer prognosis for both tumor progression and overall survival, and, consequently, the protein product N-Myc is a prime target for new drugs for NB treatment." (PMID 38730731, 2024). "Our results are derived from two tumor cell lines, one mouse and one human, that lack MYCN amplification." (PMID 38095019, 2023). "Prophylactic treatment of TH-MYCN+/+ mice with chemical inhibitors of mitosis was sufficient to largely block further tumor progression, suggesting an MYCN-specific molecular vulnerability." (PMID 37958555, 2023). "The circRNA ‘cluster 1’ was also strongly enriched with circRNAs downregulated in MYCN-amplified tumor samples (p < 1e−8)." (PMID 37402719, 2023). "In the second phase our studies showed no significant increase in serum BDNF concentration in these NB patients, with adverse pathologic features, large tumor maximum diameter, and MYCN amplification." (PMID 37460933, 2023). "The genomic amplification of the oncogene MycN is currently the most important prognostic marker of poor outcomes, rapid tumor progression and treatment failure." (PMID 36980635, 2023). "The tumor cell clusters were clearly identified based on their increased expression of human MYCN and the firefly luciferase (FLUC) reporter gene." (PMID 38001143, 2023). "This was in sharp contrast to AGM samples, indicating strong MYCN/Mycn-dependent tumor induction and progression in both, TI and TIM." (PMID 37246217, 2023). "Consistent with in vitro cellular results, depletion of BAP1 significantly retarded the growth of tumor xenografts, whereas overexpression of MYCN partially rescued BAP1 depletion-mediated cells growth inhibition." (PMID 37543638, 2023). "CENPA and TIMP1 are highly expressed in the tumor tissue of most cancers, while MYCN is usually lowly expressed." (PMID 37213288, 2023). "As a member of the basic helix-loop-helix (bHLH) family transcription factors, MYCN promotes the expression of proteins involved in cell motility, extracellular matrix degradation, and invasion, thereby facilitating tumor metastasis." (PMID 37611092, 2023). "Given the importance of CSF1 in macrophage recruitment to the TME, MYCN-amplified PDX-COJEC was xenografted to a nude mouse model to test the effect of anti-CSF1R treatment on inhibiting macrophage recruitment to NB tumours." (PMID 37887559, 2023). "The 9464D cell line is derived from the spontaneous tumor of the TH-MYCN mice and, thus, expresses high levels of MYCN, a signature of MYCN-amplified HR-NBs." (PMID 37835389, 2023).